AHR (aryl hydrocarbon receptor)
Diseases named in the same sentence as AHR in open-access papers (continued):
Sharing a sentence is not in itself a finding about the gene and the disease.
glioma (continued). "In glioma or glioblastoma, AhR expression has been positively related to malignancy and tumor promotion." (PMID 34955744, 2021). "IL4I1 promotes glioma cell migration via the Kyn/AHR pathway, and suppresses T cell proliferation in glioblastoma, which is associated with poor survival of glioma patients." (PMID 34659216, 2021). "In glioblastoma, Kyn produced by glioma cells activates AHR in TAMs leading to enhanced recruitment via CCR2 upregulation." (PMID 34831183, 2021). "The expression of AHR is the highest in GBM-relative to lower grade gliomas and is independently correlated with poor patient prognosis, thus making AHR an attractive target for GBM immunotherapy." (PMID 33668200, 2021). "IL4I1 is a metabolic, immune checkpoint that activates the aryl hydrocarbon receptor and promotes glioma progression." (PMID 34917513, 2021). "Lately, there is growing evidence that AhR plays an important part in the initiation of benign and malignant brain tumors, including gliomas, meningiomas, and medulloblastomas." (PMID 32325928, 2020). "Below we will discuss the role of AhR in the initiation of benign and malignant brain tumors, including gliomas, meningiomas, medulloblastomas and pituitary tumors." (PMID 32325928, 2020). "Mechanistically, we found that IDO1/TDO accounted for the release of Kyn, which activated AhR to promote cell motility via the Kyn–AhR–AQP4 signaling pathway in U87MG glioma cells." (PMID 32296044, 2020). "Immunostaining of the AhR in infiltrating gliomas from 73 patients showed that the AhR was expressed in all tumors with the highest staining observed in GBM." (PMID 32731514, 2020). "Human grade 4 gliomas indeed show highest AhR and NTPDase1/CD39 expression and elevated AhR expression level is associated with poor prognosis." (PMID 33613285, 2020). "All the data indicated that both IDO1 and TDO contributed to the production of Kyn, which upregulated AhR expression in glioma cells." (PMID 32296044, 2020). "Lately, there is growing evidence that AhR plays an important role in the initiation of benign and malignant brain tumors, including gliomas, meningiomas, medulloblastomas, and neuroblastomas." (PMID 32325928, 2020). "Tryptophan metabolism pathways and the AhR signaling pathway, which is activated in response to kynurenine, and some other components of the KP, are dysfunctional in gliomas and meningiomas as well as in a number of other solid tumors." (PMID 32325928, 2020). "In this study, we analysed 6 public transcriptome glioma data sets and identified three glioma prognosis-related transcription factors, AHR, NFIL3 and ZNF423." (PMID 27586240, 2016). "We investigated the relevance of the three-TF signature to regulation mechanisms of glioma carcinogenesis and suggested AHR, NFIL3 and ZNF423 as promising biomarkers for not only glioma molecular subtype diagnosis but also clinical treatment." (PMID 27586240, 2016). "In glioma cells, kynurenine induces AhR translocation into the nucleus and activates AhR target genes, but the concentrations of kynurenine used in those experiments are at least 10 times higher than those reported in uremic serum." (PMID 24599232, 2014). "Furthermore, these TCEs enhanced the invasion and migration of glioma cells by promoting the expression of AQP4 via the kynurenine/AHR signalling pathway." (PMID 40071723, 2025). "Besides, a recent study showed that glioma-derived kynurenine activates the aryl hydrocarbon receptor (AHR) in TAMs, modulating their recruitment and inducing T-cell dysfunction, while glioma stem cell-derived POSTN recruits TAMs." (PMID 41353343, 2025). "Methods/Objectives: We hypothesized that ITE could synergize with PD1 antibody as AHR is one major node of immune-suppressive pathways, and tested it using an immune-competent mouse glioma model." (PMID 40283908, 2025). "In addition, glucose deprivation triggers nuclear translocation of the AhR in HepG2 cells and increases AhR transcription in gliomas." (PMID 39457607, 2024).
glioma (continued). "Indeed, kynurenine (KYN)-induced AhR signaling in gliomas was found to affect macrophage polarization and phenotype and the AhR depletion led to increased NF-κB activation in vitro." (PMID 39211042, 2024). "IDO and TDO positively correlate with glioma grading and may promote the migration and invasion of glioma cells through the KYN/AhR/APQ4 signaling pathway." (PMID 39408347, 2024). "Furthermore, exogenous consumption of tryptophan resulted in glioma cells activating AHR which inhibited T cell function, induced T cell apoptosis, promoted CD39 expression, and induced differentiation of T cells mediated by interleukin 10 (IL-10)." (PMID 39594997, 2024). "Additionally, the remaining AHR agonists can bind to astrocytes and gliomas which results in T cell activation, the regulation of dendritic cells, and the recruitment of tumor-associated macrophages (TAMs)." (PMID 39594997, 2024). "Based on four signature genes (AHR, DACH1, MGMT, and YAP1), a risk model for predicting glioma sensitivity to temozolomide was constructed, and the results of timeROC in both the training and validation sets showed that the model had good predictive performance." (PMID 36959804, 2023). "Furthermore, inhibition of 2-hydroxyglutarate mediated immunosuppression with an AhR inhibitor in combination with ICI increased overall survival in mice with IDH mutant glioma." (PMID 36566461, 2023). "Targeting AhR in vitro led to decreased glioma cell viability." (PMID 36900311, 2023). "First, we analyzed AhR gene expression using the human glioma microarray data set GSE4290." (PMID 38068712, 2023). "The authors analyzed by microarray the transcriptome of kynurenine-treated glioma and found an AHR signature, characterized by an upregulation of AHR-target genes such as CYP1B1 (Cytochrome P450 family 1 subfamily B member 1) and TIPARP (TCDD-inducible poly-ADP-ribose polymerase)." (PMID 36188218, 2022). "Indeed, TDO2 or AhR inactivation, similarly to the hpol k knock-down, reduces chromosomal instability in glioma cell lines, as assessed by micronuclei formation." (PMID 35681770, 2022). "KYN is a natural endogenous ligand of the human aryl hydrocarbon receptor (AHR) which activates the KYN-AhR-AQP4 signaling pathway supporting tumor growth and glioma cell motility, as well as the agonistic activity in the AHR leading to the differentiation onaïveaive to Treg lymphocytes." (PMID 36355137, 2022). "Importantly, the TDO2-kynurenine-AhR axis was demonstrated to sustain hpol κ expression in glioma and to thereby drive chromosomal instability." (PMID 35681770, 2022). "Therefore, based on our data and others, the constitutive expression of AhR has multiple tumors promoting effects in certain glioma and glioblastoma cells." (PMID 34955744, 2021). "Thus, Imaging-Community-AMARETTO (Appendix Fig A1) identified THBS1 and MAP2 as novel master drivers across the three STAT3, AHR, CCR2, and OLIG2 communities that provide new insights into how these distinct key mechanisms are linked in glioma." (PMID 32383980, 2020). "The role of AhR in tumor growth is confirmed by the slower growth of TDO2-expressing tumors in AhR-deficient mice and the abrogation of clonogenic survival in response to kynurenine in AhR knockdown glioma cells." (PMID 32325928, 2020). "Interestingly, all AHR SNPs described so far reside in exon 10, encoding the TAD, and are associated with other neoplasms, including gliomas." (PMID 33281746, 2020). "TDO2 is overexpressed in human glioma cells, and this phenomenon correlates with the production of kynurenine and with the expression of AhR target genes, thus indicating the production of a sufficiently large amount of kynurenine for AhR activation." (PMID 32325928, 2020). "Activation of AhR through TDO-derived Kyn is a novel mechanism to support tumor growth in gliomas." (PMID 32296044, 2020). "Myeloid-specific deletion of AHR in mice blunted BM-TAMs glioma infiltration." (PMID 33154756, 2020).
glioma (continued). "Since DOC2A has been reported as a suppressor gene in many carcinomas such as colorectal cancer and urothelial cancer, we suggest AHR might promote glioma progression through inhibiting the tumor suppressor gene, DOC2A." (PMID 27586240, 2016). "Aryl hydrocarbon receptor (AhR) is a ligand-dependent transcription factor expressed by cells of the immune system and many types of human tumors, including urothelial, prostate, breast, ovarian, gastric, liver, pancreatic, lung, medulloblastoma, glioma and T-cell leukemia." (PMID 38169949, 2023). "Meanwhile indoleamine 2,3-dioxygenase (IDO)-1/2 and tryptophan 2,3-dioxygenase (TDO)-2 were highly expressed in glioma cells and were proportional to tumor grade, which catalyzed the decomposition of Trp into kynurenine (Kyn), a ligand of the aryl hydrocarbon receptor (AHR)." (PMID 34211978, 2021). "Thus, the pathogenesis of gliomas may include altered regulation of AhR, which may be a promising target for the treatment of malignant human gliomas and other diseases associated with a pathological activity of TGF-β." (PMID 32325928, 2020). "It has been shown on glioma cell lines that AhR promotes the development of a malignant phenotype of glioma cells at the level of proliferation, clonogenicity, and invasiveness: these properties weaken during exposure to a low-molecular-weight inhibitor of AhR (CH-223191) or after an AhR knockout." (PMID 32325928, 2020). "Nonetheless, the use of small-molecule compounds to modulate IDO1/2, TDO2, and AhR in glioma and meningioma cell lines has already proven that in contrast to enzyme inhibition, AhR antagonists markedly reduce tumor cell viability, i.e., AhR may be a therapeutic target in these types of cancer." (PMID 32325928, 2020). "The level was slightly increased upon ITE treatment of GL261 cells in vitro but remained unchanged in glioma tissues of all groups, indicating that ITE exerts its effects via AHR." (PMID 40283908, 2025). "This review interrogates the impact of the gut microbiota on glioma, focusing on critical pathways such as NF-κB, MAPK, PI3K/Akt/mTOR, and Kynurenine/AhR that drive tumor proliferation, immune evasion, and therapy resistance." (PMID 40075568, 2025). "Recent studies have demonstrated that IL4I1 activates AhR more potently than IDO1 and TDO2, generating indole metabolites and quinolinic acid that promote tumor progression in gliomas and leukemia by enhancing cancer cell motility and suppression immunity." (PMID 40559961, 2025). "Conversely, in glioma, elevated TDO2-derived Kyn engages AhR to potentiate PI3K-Akt signaling and accelerate malignant cell proliferation." (PMID 40963608, 2025). "For instance, in data derived from the Rembrandt database, patients with gliomas (WHO grades II–IV) exhibiting high expression of TDO2 and AhR had considerably lower survival rates compared to those with intermediate or low expression." (PMID 38951170, 2024). "The expression of CD39 is promoted by AHR in GAMs, which promotes CD8+ T cell dysfunction by cooperating with CD73 to produce adenosine in the immune microenvironment of glioma." (PMID 34659216, 2021). "In glioma, IDO1/TDO was shown to account for Kyn release and subsequent AhR-activation mediated cell motility via the expression of aquaporin 4 (AQP4)." (PMID 33451095, 2021). "Additionally, changes in AhR and AhR target gene levels have been linked to increased IDO1 and TDO2 levels in glioblastoma cells pointing to the fact that increased IDO-activity might promote AhR-mediated changes in glioma cells that enable immune escape and malignant potential." (PMID 34819875, 2021). "But another study reported that overexpression of MYH9 abrogated the migration-inhibiting effects of the endogenous aryl hydrocarbon receptor agonist, indicating that MYH9 is essential for glioma cell migration." (PMID 34887392, 2021).
glioma (continued). "Omeprazole inhibits GBM cell invasion and migration through acceleration of tumor-suppressive properties of the aryl hydrocarbon receptor (AhR) which is expressed in GBM in vitro and in a subcutaneous PDX glioma mouse model." (PMID 34203660, 2021). "The released Kyn induced the expression of CCR2 by activating AHR, and advanced the recruitment of macrophages to tumor sites by enhancing the response to MCP-1 secreted by glioma cells." (PMID 34211978, 2021). "Consistently, the myeloid-specific deletion of AHR results in the improved rates of mouse survival and decreases the tumor burden in response to the GL261 glioma orthotopic implantation." (PMID 34831183, 2021). "The expression levels of IDO1, TDO, AhR, and AQP4 in the tumor areas of GL261 orthotopic glioma mice were higher than those in the corresponding brain tissue from healthy mice." (PMID 32296044, 2020). "Using a glioma cell line, we found that both IDO1 and TDO contributed to the production of Kyn, which upregulated AhR expression and regulated the migration and invasion of glioma cells." (PMID 32296044, 2020). "Using the U87MG glioma cell line, we found that IDO1/TDO accounted for the production of Kyn, which activated AhR to promote cell motility via the Kyn–AhR–AQP4 signaling pathway and modulated the cell area and cytoskeleton." (PMID 32296044, 2020). "In terms of the role of TDO in cancer, TDO is strongly expressed in various cancers including glioma and TDO-derived Kyn promoted glioma cell survival and migration thorough the aryl hydrocarbon receptor (AHR) activation in an autocrine/paracrine fashion." (PMID 32050636, 2020). "Kynurenine production by glioma-derived TDO inhibited anti-tumor immune responses and augmented survival and motility of tumor cells in an AHR-dependent manner." (PMID 30501068, 2018). "We revealed a novel three-transcription-factor signature including AHR, NFIL3 and ZNF423 for glioma molecular subtypes." (PMID 27586240, 2016). "Recently, kynurenine (kyn), a tryptophan catabolite that is constitutively produced in glioma cells by tryptophan-2,3-dioxygenase (TDO) in amounts sufficient for AhR activation, has been identified as an endogenous ligand of AhR." (PMID 24932473, 2014). "Studies demonstrated that AhR activation, induced by tryptophan metabolism and Kyn accumulation, enhances tumor cell proliferation and invasion in patient-derived glioma samples and human GBM cell lines, findings that highlight the AhR as a promising therapeutic target for glioblastoma treatment." (PMID 40149846, 2025). "Furthermore, ITE bound to AHR and inhibited the transcription of POU5F1 in glioma stem cells, which led to the inhibition of tumor growth in the U87MG xenograft glioma model." (PMID 40283908, 2025). "Importantly, the inhibition of AhR successfully restores a pro-inflammatory, anti-tumor macrophage phenotype in IDH-mutant gliomas, and combining AhR inhibitors with anti-PD-L1 immunotherapy synergistically enhances therapeutic outcomes." (PMID 40427130, 2025). "Additionally, caution must be exercised when extrapolating findings from mouse glioma models to GBM patients, as there are significant differences in the AHR pathway between mice and humans." (PMID 40283908, 2025). "AHR is known to mediate immune-suppressive functions of certain tryptophan metabolites such as kynurenine; yet, there lack of reports on how AHR agonists affect glioma immunity." (PMID 40283908, 2025). "Based on the significant correlation between tryptophan metabolism and glioma development as well as TMZ efficacy, we speculate that IDO1 and AHR are the potential targets in bacterial tryptophan metabolism." (PMID 36927689, 2023). "At the same time, AHR in DC and TAM can also act on CD8+T cells to regulate the growth of glioma." (PMID 36003766, 2022).
glioma (continued). "The aryl hydrocarbon receptor (AHR) is a ligand-activated transcription factor involved in regulating cell metabolism, proliferation, differentiation, cell death, and cell adhesion, which is widely and highly expressed in gliomas, especially in GBM." (PMID 36003766, 2022). "Although the TDO–Kyn–AhR signaling pathway has been reported to promote glioma migration and invasion, the exact mechanism was not clear." (PMID 32296044, 2020). "Established GBM cell lines also express the AhR, however, our recent study identified a patient-derived glioma cell line (PDG 14-015s) which did not express the AhR." (PMID 32731514, 2020). "Glioma cells instruct this pathway through indoleamine 2,3-deoxygenase (IDO)-dependent production of kynurenine (KYN), a metabolite that triggers CCR2 upregulation through aryl hydrocarbon receptor (AHR)." (PMID 33154756, 2020). "For the first time, we demonstrated that the IDO1/TDO–Kyn–AhR signaling pathway could regulate AQP4, which is involved in the migration and invasion of glioma cells." (PMID 32296044, 2020). "Based on our inferred differential networking information and the previously reported signalling knowledge around our signature genes, we generated testable hypotheses on the roles of AHR and NFIL3 in glioma carcinogenesis." (PMID 27586240, 2016). "We also proposed some testable hypotheses on the roles of AHR and NFIL3 in glioma carcinogenesis which are worthy of further experimental investigations." (PMID 27586240, 2016). "The expression values of AHR, NFIL3 and ZNF423 across glioma subtypes are significantly different." (PMID 27586240, 2016). "According to our inferred differential networking information and previously reported signalling knowledge, we suggested testable hypotheses on the roles of AHR and NFIL3 in glioma carcinogenesis." (PMID 27586240, 2016). "Thus, The Kyn–AhR axis also influences AQP4 expression by favoring the upregulation of the M1-AQP4 isoform, thus reinforcing the pro-invasive and therapy-resistant phenotype of glioma cells." (PMID 41324079, 2025). "While we did not assess AhR expression modulation in this study, future research should investigate how additional factors may impact AhR expression and signaling pathways in glioma cells." (PMID 40149846, 2025). "Interestingly, R-2-hydroxyglutarate (R-2-HG), a metabolite that accumulates in isocitrate dehydrogenase (IDH)-mutant gliomas, enzymatically induces TDO in tumor-infiltrating myeloid cells, leading to AhR-dependent suppression of macrophage function and anti-tumor immunity." (PMID 38807762, 2024). "Therefore, we checked if these three transcription factors (AHR, NFIL3 and ZNF423) could be a glioma prognosis-related signature by measuring its clinical relevance with NMF clustering method and survival analysis." (PMID 27586240, 2016). "The motility of glioma U87MG cells was increased when AQP4 was overexpressed or Kyn was supplemented, while Kyn supplementation could not restore the cell motility decreased by AhR inhibition and AQP4 knockdown." (PMID 32296044, 2020).